ALK (ALK receptor tyrosine kinase)
Diseases named in the same sentence as ALK in open-access papers (continued):
Sharing a sentence is not in itself a finding about the gene and the disease.
lung cancer (continued). "ALK inhibitors were demonstrated to drastically increase lung cancer survival, but there is a lack of clinical and molecular prognostic and predictive biomarkers." (PMID 37444532, 2023). "To define the role of the tumor microenvironment (TME) in mediating response to TKI therapy in ALK positive lung cancer, we have used an orthotopic immunocompetent model whereby murine EML4-ALK fusion-positive lung cancer cells are directly implanted into the lungs of syngeneic C57BL/6 mice." (PMID 36739466, 2023). "Lung cancers with confirmed ALK rearrangements often contain regions that are ALK-negative according to a previous study." (PMID 37511126, 2023). "Many trials supported pembrolizumab as a first-line monotherapy to significantly improve overall survival (OS) in selected patients with previously untreated metastatic Non–Small Cell Lung Cancer (mNSCLC) and a PD-L1 TPS of ≥50% without EGFR/ALK mutations." (PMID 37189193, 2023). "Our results showed that NF1 mutations had no direct effect on OS in LUAD cases or LUSC cases, even in lung cancer patients without driver genes (EGFR mutations and ALK fusion)." (PMID 35702826, 2023). "Asian patients with adenocarcinoma have higher prevalence of unique biologic features such as a higher incidence of oncogene-driven NSCLC (mainly EGFR-mutant and ALK-rearranged tumors), and the majority of Asian women with lung cancer are never-smokers." (PMID 36650586, 2023). "A one-step reverse transcription-polymerase chain reaction to examine the presence of the METex14 mutation was performed using RNA samples from 1374 lung cancer patients with no detected EGFR and ALK mutations." (PMID 36969059, 2023). "The first and largest sample size study was published in 2016, including 80 never-smoking lung cancer patients who had ALK translocation assessed." (PMID 37610496, 2023). "Notably, KRAS, BRAF, ERBB2, PIK3CA, RET, ROS1, ALK, and NRTK1/2/3 have been proposed as prognostic markers, making substantial contributions to genotype-directed therapies for advanced lung cancer." (PMID 36619227, 2023). "However, SCLC transformation can also occur in anaplastic lymphoma kinase (ALK)-positive lung cancer after treatment with ALK inhibitors and in wild-type EGFR or ALK NSCLC treated with immunotherapy." (PMID 38067352, 2023). "Although tyrosine kinase inhibitor (TKI) therapy shows marked clinical efficacy in patients with anaplastic lymphoma kinase–positive (ALK+) and ROS proto-oncogene 1–positive (ROS1+) non–small cell lung cancer (NSCLC), most of these patients eventually relapse with acquired resistance." (PMID 37917191, 2023). "ALK overexpression is found in several cancers included but not limited to ovarian, progressive neuroblastoma, lung cancer, and cholangiocarcinoma." (PMID 38144528, 2023). "Despite the promising efficacy and tolerability of alectinib in treating advanced anaplastic lymphoma kinase (ALK) positive non-small cell lung cancer (NSCLC), the role of alectinib in neoadjuvant setting remains understudied in ALK-rearranged resectable lung cancer." (PMID 37409244, 2023). "There has been the number of molecular alterations identified in lung cancer including oncogenes and tumor suppressor genes, such as Epidermal Growth Factor Receptor (EGFR), Anaplastic Lymphoma Kinase (ALK) which have high relative frequencies as molecular targets." (PMID 36990974, 2023). "Recent studies reported that patients with EGFR/ALK/ROS1 mutation, bone metastasis, and no immune-related adverse events had poor prognosis during immunotherapy in lung cancer." (PMID 37790758, 2023). "None of the 1293 lung carcinomas with driver alterations in EGFR/ALK/ROS1/RET/MET oncogenes had NTRK 5′/3′-end expression imbalances." (PMID 37762506, 2023). "ALK and RET gene rearrangements are particularly frequent in lung carcinomas." (PMID 37686416, 2023).
lung cancer (continued). "The discovery of druggable targets such as epidermal growth factor receptor (EGFR), anaplastic lymphoma receptor tyrosine kinase (ALK), MET, ROS-1receptor tyrosine kinase and Kirsten rat sarcoma viral oncogene homolog (KRAS) open avenues for treating lung cancer." (PMID 35743687, 2022). "Women present more often with adenocarcinoma histology and EGFR/ALK alterations, as lung cancer in never-smokers is more common in women compared to men." (PMID 35884463, 2022). "A retrospective study reported no responses in the six ALK-rearranged lung cancer patients evaluated, while in a retrospective multicenter French study, only two of eight ALK-rearranged patients achieved a response." (PMID 35407463, 2022). "This is not the case in lung cancer with an anaplastic lymphoma kinase (ALK) fusion, where survival data are comparable between men and women." (PMID 35884463, 2022). "Known ALK/ROS1 fusions and 5′‐/3′‐end unbalanced expression were analyzed in 2009 EGFR mutation‐negative non‐small cell lung cancer (NSCLC) samples with RT‐PCR tests, which were optimized for the use with FFPE‐derived RNA." (PMID 35322575, 2022). "Known ALK/ROS1 fusions and 5’‐/3’‐end mRNA unbalanced expression were analyzed in 2009 EGFR mutation‐negative non‐small cell lung cancer (NSCLC) samples." (PMID 35322575, 2022). "In a phase II trial (ATLANTIC), no responses were observed in 15 ALK-rearranged lung cancer patients treated with durvalumab, regardless of PD-L1 expression." (PMID 35407463, 2022). "Anaplastic lymphoma kinase (ALK)-positive lung cancer is a rare cancer that occurs in approximately 5% of non-small-cell lung cancer (NSCLCs) patients." (PMID 36612200, 2022). "For the clinical and scientific community, the answer is clear: the pursuit of ALK lung cancers, as for any cancer or terminal health condition, does not stop until cure and then prevention are reached comfortably and reliably at 100%." (PMID 36003760, 2022). "However, in the future, 10% of patients with non-smoking NSCLC should be included in different molecular studies, which will show that NSCLC’s origin is more significant than the already known oncogenic drivers of lung cancer, such as EGFR, ALK, or ROS1." (PMID 35203569, 2022). "In line with studies on ALK-positive lung cancers, which have showed the variable clinical outcome of patients with different EML4-ALK fusion variants, we also observed prolonged PFS outcome in patients harboring the v1 variant compared with those carrying the v3 variant." (PMID 36369474, 2022). "ALK positive lung cancer is a rare cancer that occurs in approximately 5% of non-small-cell lung cancer (NSCLCs) patients." (PMID 36612200, 2022). "The current College of American Pathologist (CAP)/International Association for the Study of Lung Cancer (IASLC)/Association for Molecular Pathology (AMP) guidelines recommend screening advanced-stage lung cancer patients for targetable alterations including testing for EGFR, ALK, and ROS12." (PMID 36057739, 2022). "Rebiopsy, for NGS testing to ascertain ALK resistance profiles, has not been widely available; however, it is often performed in high-volume lung cancer and academic centers." (PMID 36003760, 2022). "Women present more often with adenocarcinoma histology and EGFR/ALK alterations, as lung cancer in never-smokers is more common in females." (PMID 35884463, 2022). "ALK rearrangements may oncogenically drive LCNEC, a rare and clinically aggressive subtype of lung cancer, sensitizing this tumor to treatment with ALK inhibitors." (PMID 35756632, 2022). "While our retrospective biomarker analysis was fairly comprehensive, it is limited due to several factors, including that many lung cancers were diagnosed before molecular testing for biomarkers, such as EGFR, ALK, ROS1 and others, were considered standard of care." (PMID 35805276, 2022).
lung cancer (continued). "Similarly, in lung cancer, an oncogenic fusion of EML4/ALK generated a fusion circRNA, F-circEA-2a, which was shown to exhibit tumor promotion properties in lung cancer development." (PMID 35205610, 2022). "However, it is hard to reconcile pre-existing resistance with remission that lasts for months and years before re-emergence of rapidly growing tumors (most patients on front line therapies in ALK+ and EGFR mutant lung cancers)." (PMID 35078159, 2022). "The efficacy difference between the second‐ and third‐generation of anaplastic lymphoma kinase‐tyrosine kinase inhibitors (ALK‐TKIs) after crizotinib failure in advanced ALK‐positive non–small cell lung cancer (NSCLC) has not been clarified." (PMID 35560808, 2022). "The second change in paradigm for advanced lung cancer patients with ALK translocation is the recognition that prognosis is not influenced by brain metastasis, and the treatment up front should be a systemic, radiation-free treatment for most cases." (PMID 35806325, 2022). "The advent of multiple molecular targets in advanced NSCLC has brought about new treatments, but no cases of cCR in advanced ALK-positive lung cancer after multiple lines of conversion therapy have been reported." (PMID 36523965, 2022). "Besides the sensitive detection of SNVs and INDELs, gene fusions in ALK, RET, or ROS1 were detected in 2.9% of ctDNA-positive lung cancer cases, exemplifying the clinical applicability of an amplicon-based assay for the detection of novel fusions." (PMID 35486650, 2022). "Molecular profiling of lung cancer samples for activated oncogenes, including epidermal growth factor receptor (EGFR), anaplastic lymphoma kinase (ALK) and c–ros oncogene 1 (ROS1), is considered as standard-of care to select the most appropriate up-front treatment." (PMID 36551608, 2022). "KRAS, ROS1, ALK, and EGFR are the main biomarkers affecting clinical practice of lung cancer." (PMID 36260870, 2022). "At the same time, we tested the expression of ALK and TOPK in various lung cancer cells." (PMID 36167821, 2022). "STAT3 activity was restored and stably maintained upon initial ALK-TKIs (alectinib, ceritinib, lorlatinib, and brigatinib) treatment in the absence of ALK signaling, characterizing the treatment-induced adaptive survival of ALK-rearranged lung cancer cells." (PMID 35228642, 2022). "As opposed to MET alterations, ALK fusions represent a well-established therapeutic target in lung cancer, as they are detected in 3–7% of NSCLCs and have been associated with an absence of smoking, younger age, and adenocarcinoma histology." (PMID 35012520, 2022). "ALK and BTK are the two major targets for inhibition of lung cancer and attraction for the receptor to develop novel drug molecules against the patient suffering from lung cancer as well as SARS-COV-2." (PMID 35356629, 2021). "In lung cancer, for example, a study of 5,688 patients with non–small-cell lung cancer from 2011 to 2016 demonstrated that 15.4% received broad-based genomic sequencing and 84.6% received single gene testing for EGFR and/or ALK." (PMID 34651094, 2021). "All of the clinically-relevant variants of the EGFR, ALK, BRAF and KRAS genes are unambiguously lung cancer-associated and do not meet CHIP criteria; therefore, the presence of CHIP-associated variants doesn’t affect clinical decision making." (PMID 34031447, 2021). "It is tempting to speculate that this putative disadvantage from early exposure to chemotherapy might be even more important for ALK+ lung cancers compared to other NSCLC, because of the particularly low baseline TMB of ALK+ disease." (PMID 33494549, 2021). "Moreover, finding target molecules, such as epidermal growth factor receptor (EGFR), anaplastic lymphoma kinase (ALK), ROS1, and programmed death ligand 1 (PD-L1), is significantly important for making treatment decisions in patients with lung cancer." (PMID 34441366, 2021).
lung cancer (continued). "Brigatinib was compared with crizotinib in a phase 3 trial in patients with ALK-positive lung cancer who had not been previously treated with TKI." (PMID 33435596, 2021). "During the past 20 years, important progress has been made in our understanding of the molecular pathogenesis of lung cancer, whose malignant transformation has been demonstrated to result from the accumulation of genetic aberrations such as in EGFR, KRAS, and ALK." (PMID 33288886, 2021). "Despite the absence of a direct correlation between ALK fusions and bone metastasis, the detection of these rearrangements contributes to the classification of target therapies for lung cancer patients with bone metastasis." (PMID 34722241, 2021). "Moreover, patients with ALK-positive lung cancer have a higher incidence of brain metastasis, whereas patients with ROS1-positive lung cancer have a lower incidence." (PMID 34205733, 2021). "Second, the main targets of clinical lung cancer targeted drugs are EGFR, ALK, etc.." (PMID 34681590, 2021). "Interestingly, the ALK inhibitor Ceritinib decreased mTOR activity and increased GFP-WIPI1 dot formation in H3122 and H2228 EML4-ALK+ lung cancer cells, suggesting autophagy activation." (PMID 33907223, 2021). "Tissue sampling could originally only establish the diagnosis of lung cancer, but now sufficient tissue sampling is needed for next generation sequencing for epidermal growth factor receptor (EGFR), anaplastic lymphoma kinase (ALK), ‐etc‐." (PMID 32949105, 2021). "Patients with ALK-positive lung cancer appear to have a worse prognosis than those without ALK fusion." (PMID 34234236, 2021). "It is not surprising that, of those young patients with advanced lung cancer, there would be an enriched population of ALK positive patients and that was confirmed in the evaluation of this dataset." (PMID 34786182, 2021). "Non-small cell lung cancer (NSCLC) accounts for approximately 85% of lung cancer cases, and of these, approximately 2–7% are anaplastic lymphoma kinase (ALK), with the majority being of the nonsquamous subtype." (PMID 34136409, 2021). "Finally, we detail the current landscape of additional actionable alterations (EGFR, ALK, ROS1, MET) in lung cancer, a biomarker-rich malignancy that has greatly benefitted from the precision oncology revolution." (PMID 34198738, 2021). "The NCCN guidelines and the Japanese guidelines for the treatment of lung cancer recommend alectinib as first-line therapy for advanced NSCLC without ALK-p ALK inhibitors, whereas lorlatinib is not approved as a first-line therapy." (PMID 34359604, 2021). "Significant overexpression of SPP1 protein in ALK-positive lung cancer was confirmed by IHC compared to paired adjacent normal tissues and ALK-negative cancers." (PMID 34234236, 2021). "In lung cancer, a different LMO7‐ALK variant, L15:A20, was reported in molecular analysis of 158 ALK‐rearranged NSCLCs but no treatment information and clinical follow‐ups were available." (PMID 34541785, 2021). "Moreover, we determined the expression of PGK1 with several typical genetic alteration events in lung cancer, including EGFR mutants, KRAS mutants, and ALK fusions in The Cancer Genome Atlas (TCGA) clinical cohort." (PMID 34091600, 2021). "Approximately 80–85% of lung cancers count among non-small cell histology (NSCLC), and approximately 2–7% of NSCLC cases feature positivity for anaplastic lymphoma kinase (ALK) gene rearrangement or connection with echinoderm microtubule-associated protein-like 4 (EML4)." (PMID 33572278, 2021). "Targeted next-generation sequencing approaches (NGS) have proven to be affective in the detection of chromosomal aberrations like translocation of ALK and lysine methyltransferase 2A (KMT2A) in lung carcinoma, anaplastic large cell carcinoma and acute leukemias." (PMID 33946969, 2021).
lung cancer (continued). "The Lung-molGPA scoring system was recently introduced for oncogenic-driven brain metastasized lung cancer, but has not yet been validated in cohorts including only ALK-translocated tumors." (PMID 32640547, 2020). "Targeted therapy has provided a positive outcome for lung cancer patients with epidermal growth factor receptors (EGFR), anaplastic lymphoma kinase (ALK), ROS proto‐oncogene 1 receptor tyrosine kinase (ROS1) and B‐Raf proto‐oncogene serine/threonine kinase (BRAF) mutations." (PMID 31975535, 2020). "In regard to the relationship between the status of EGFR and ALK (EGFR mutations, ALK fusions and EGFR/ALK co-alterations) and the clinical pathological features of patients with lung cancer, there are not many studies conducted." (PMID 33520689, 2020). "Other potential explanations include the existence of multiple primary lung cancer lesions, tumor heterogeneity, and the clonal evolution of tumor cells, related or not to ALK TKI therapy." (PMID 32674491, 2020). "Tumors with mutations in BRAF (7% of lung cancers) may be treated with vemurafenib or dabrafenib, and tumors with rearrangements involving ALK and/or ROS1 (1–2% of lung cancers) may be treated with crizotinib, ceritinib or alectinib." (PMID 32898185, 2020). "Notably, lung cancer with ALK rearrangement represents only a small subset of NSCLC, but metastatic ovarian tumors were found to occur in most ALK fusion-positive cases." (PMID 31455365, 2019). "Most mutations detected in CSF samples could be found in FFPE samples except for ALK G689R in 2 individuals and KRAS Q61L in 1 individual, demonstrating that most tumors in the brain originated from the primary lung cancer." (PMID 30755180, 2019). "We demonstrated that the transcription levels of ALK- or RET-fusion partner genes, such as EML4, CCDC6 and KIF5B, were constitutively activated in lung cancer cells, and the expression at the C-terminal region of ALK, RET, or ROS1 was also markedly elevated in each fusion-positive lung cancer cell." (PMID 30943926, 2019). "We found that the promoter of EML4 was constitutively activated in lung cancer as well as normal cells independent of ALK fusion, and C-terminal ALK protein level and phosphorylation were specifically elevated in ALK fusion–positive cancer cells." (PMID 30943926, 2019). "This strategy has been successful in vitro and in vivo in targeting the Ras/MAPK, EGFR, and IGF-1R kinases in ALK fusion-positive lung cancer, but is not yet applied in the clinic." (PMID 30813562, 2019). "Kirsten rat sarcoma (KRAS) mutations occur in about 30% of lung adenocarcinomas, and unlike other common oncogenic drivers (such as epidermal growth factor receptor (EGFR) and anaplastic lymphoma kinase (ALK)), effective targeted therapeutic strategies for KRAS mutant lung cancer have been limited." (PMID 30986992, 2019). "Females with lung cancer are more likely than males to be never-smokers, have adenocarcinoma with an activating EGFR or ALK mutation, which increase the risk of distant metastasis." (PMID 31822734, 2019). "Previous studies have shown that young patients with lung cancer have a lower incidence of epidermal growth factor receptor (EGFR) mutations and a higher incidence of anaplastic lymphoma kinase (ALK) fusions, but not all studies have reported the same results." (PMID 31387567, 2019). "For one patient (LTO_16), molecular examination of the ovarian tumor was not performed, but the lung cancer harbored an ALK rearrangement." (PMID 31455365, 2019). "Also the prevalence of the RET fusions greatly increases (from a median 1.8% to a significative 6.3%) when evaluated in 159 lung cancer patients wild type for EGFR, ALK, ROS1, BRAF, KRAS, HER2." (PMID 29455670, 2018). "Similarly, in KRAS-mutant lung cancers, PFS (5.0 months, 95% CI 3.67–6.33) was inferior compared with EGFR-mutant (6.5 months, p = 0.242) and ALK/ROS1-rearranged (9.2 months, p = 0.007) lung cancers." (PMID 29587667, 2018).